CD28 (CD28 molecule)
Diseases named in the same sentence as CD28 in open-access papers (continued):
Sharing a sentence is not in itself a finding about the gene and the disease.
tumor (continued). "Among genes encoding costimulatory molecules, CD70 and CD80 were similarly expressed by FL and normal GC B cells, while CD86 was significantly overexpressed in tumor cells (p = 0.004), and could contribute to the activation of Tfh after binding to CD28." (PMID 33028033, 2020). "Another well-known form of ACT, known as Chimeric Antigen Receptors (CARs) are constructed by linking variable regions of tumor-reactive antibody to intracellular signaling chains such as CD3-zeta, including costimulatory domains encoding CD28 or CD137 to fully activate T cells." (PMID 32220256, 2020). "CARs are synthetic receptors that typically contain the following parts: an antibody-derived targeting ectodomain that recognizes tumor antigens; a costimulatory molecule region that can bind to receptors such as CD28, 4-1BB, or CD278;220 and a T cell signaling domain." (PMID 32296011, 2020). "To address how MSCs impact a tumor specific CAR T cell attack, we engineered T cells with a second generation CD28Δ-ζ CAR that is deficient in IL2 secretion due to a mutation in the lck binding domain of CD28." (PMID 32260097, 2020). "Nevertheless, PD-1–mediated inhibition of CD28 co-stimulation may attenuate anti-cancer immune responses at sites of immune priming, a critical step in initiating anti-tumor immunity." (PMID 33077516, 2020). "Taken together these results suggest that expression of fluorescent protein fusion proteins in tumor cells may diminish the impact of the CD28 TM dimerization motif on CD28 cell surface expression." (PMID 32765524, 2020). "Notably, CD80 and CD86, which are expressed on both tumor cells and TILs, can interact with CD28 on T cells to activate costimulatory signaling and with CTLA-4 on activated T cells to initiate inhibitory signaling." (PMID 31771653, 2019). "Furthermore, using anti-CD28 in cancer impairs TI T-reg differentiation and function, reducing their capacity to suppress anti-tumor immune responses and promoting tumor control." (PMID 31547627, 2019). "Furthermore, we confirmed the independent predictive value of the CD8+CD28+ T-cell count in predicting tumor response to SABR in 41 patients 6 months after treatment (OR 0.08, 95% CI 0.01–0.85; P = 0.039)." (PMID 30971280, 2019). "Although CD8α and CD28 spacers have been extensively utilized in numerous clinical anti-CD19-CAR trials demonstrating potent anti-tumor efficacy, the impact of these hinges on CAR T cell performance has not been thoroughly investigated as of yet, thus their use remains largely empirical." (PMID 31108883, 2019). "However, this was accompanied by the acquisition of an exhausted phenotype and reduced anti-tumor efficacy in vivo when lower numbers of CD28-CAR T cells were transferred." (PMID 31108883, 2019). "A pre-SABR CD8+CD28+ T-cell count could predict early tumor response to SABR in patients with lung metastases from NSCLC." (PMID 30971280, 2019). "Additional Post‐BALB/cnu/nu hosts were established and injected three times around 231‐tumor challenges with neutralizing mAb of anti‐αβTCR, anti‐Vγ1TCR/‐Vγ4TCR, or anti‐CD28, with normal IgG as control Ab to see if ETSB‐primed peripheral defense axis revival would be deterred by TCR blockade." (PMID 31832307, 2019). "Additionally, a recent study showed that CD19-directed CAR-T cells initially activated in vitro with optimal stimulation (anti-CD3/CD28) progressively acquired an “exhausted” phenotype upon transfer in tumor bearing mice." (PMID 31766350, 2019). "The interaction of CTLA-4 and its ligands generates an inhibitory signal and decreases or represses the viability of T cells.Blocking the interaction of CTLA-4 and ligandspromotes CD28 to bind the two ligands, activates T cells, improves the body’s immune response, and kills tumor cells." (PMID 30564277, 2018). "This hypothesis is supported from our experiments using CD80+/CD86+ Raji tumor models, which provides comparable CD28 costimulation to both CAR-T and AbTCR-T cells." (PMID 30479831, 2018).
tumor (continued). "The group has shown, as a proof of concept, that the P60 Foxp3 inhibitor peptide can be conjugated with a CD28 targeting aptamer for delivering the peptide to CD28-expressing cells, thus inhibiting T regulatory cells when they are hijacked by the tumor micro-environment to evade the immune response." (PMID 29928493, 2018). "CD8+ Treg, in particular those expressing the CD8+CD28-CD127lowCD39+ phenotype, are regulatory T lymphocytes found highly concentrated within tumor microenvironment, where they can exert remarkable immunosuppressive activity due to their capacity to target T cell proliferation and cytotoxicity." (PMID 30459765, 2018). "Immunologically, CD8+CD28+ T cells, when activated, destroy virus-infected cells and tumor cells." (PMID 30479641, 2018). "Only the cytokines GM-CSF, IFN-γ, IL-2, IL-4 and TNF-α were detected at relevant concentrations in the presence of UniCAR CD28/ζ-armed T cells, tumor cells and TM substantiating that cytokine secretion occurs in a strictly TM- dependent- and target-specific manner." (PMID 29484126, 2018). "As the CD28/B7 co-stimulatory pathway is crucial for effective therapy with PD-1 blockade, IL PV-10 may enhance the ability of DC to stimulate tumor-reactive T cells at the tumor site." (PMID 29694419, 2018). "Assessment of expression of genes encoding the TNF receptor superfamily members as well as the immunoglobulin receptor superfamily revealed upregulation of genes encoding CD28, ICOS, 4-1BB, GITR, OX40, CD27 and CD40 within the NDV-injected tumours, with ICOS being most prominent." (PMID 28194010, 2017). "Researches have demonstrated that CD4+ CD25+ Foxp3+ Tregs inhibited proliferation, activation, degranulation, and production of granzyme A, granzyme B, and perforin of CD8+ T cells induced by anti-CD3/CD28 antibodies and are potent suppressors of autologous tumor-specific T cell responses." (PMID 28399886, 2017). "Thus, the use of “young”, less differentiated T cells with longer telomeres, high expression levels of CD27 and CD28 and potent tumor lytic activities is crucial for success." (PMID 28523432, 2017). "While these CD3/CD28 activator beads deliver robust expansion of engineered tumor-reactive T cells, development of antigen-specific expansion platforms to transfer autologous tumor-specific T cells is a long-term goal within the field." (PMID 28825053, 2017). "In addition, in the same study, the authors showed the potential of the dimeric CD28 aptamer to enhance the anti-tumor effect of the intradermal (Id) vaccine in A20 lymphoma-bearing mice following a vaccination protocol." (PMID 28325295, 2017). "The CAR used by Sung Hee Yoon at al. in a study in which CIK cells were redirected against ErBb2 tumor targets contained a different anti-ErbB2 antibody fragment but was also joined to the intracellular portions of CD28 and CD3ζ, as was the case for the CAR construct used in our study." (PMID 29029499, 2017). "Specifically, we showed that tumor cell lines derived from various tissues directly induce phenotypic and functional changes associated with T cell dysfunction characterized by the loss of CD27 and CD28 expression and telomere shortening." (PMID 28806909, 2017). "CD28 expression has been reported to correlate with tumor progression in multiple myeloma." (PMID 26918337, 2016). "To that end, we generated CD28Aptvax, consisting of irradiated tumor cells coated ex vivo with bi-specific aptamer that binds to cell-surface protein on tumor cells (MRP1) while the other part of the aptamer provides the costimulatory receptor stimulus (CD28 agonist)." (PMID 26992239, 2016). "However the conjugation of P60 with the CD28 aptamer favors the accumulation of the P60 peptide in T lymphocytes, improving the efficacy and eliciting a potent antitumor immune response upon tumor antigen vaccination." (PMID 27783034, 2016).
tumor (continued). "Finally, CD28 expression with different intensities in the tumor cell cytoplasm was observed in 187 (97.9%) patients, and CD28 expression with different intensities in the lymphocyte cytoplasm was observed in 178 (93.2%) patients." (PMID 26918337, 2016). "Also, a similar CD44low CD62L+ arrest was observed in CD8+ T cells activated with anti-CD3/CD28 and co-cultured with tumor-MDSC or bone marrow-derived MDSC (BM-MDSC), confirming the inhibitory effect of MDSC on TEFF differentiation." (PMID 27007050, 2016). "Different co-stimulatory (e.g., CD28) and co-inhibitory (e.g., CTLA-4) signal 2 molecules directs differentiation to different avenues, ranging from a potent anti-tumor response (in CD28 activation), to anergy and even apoptosis (upon CTLA-4 or Fas activation)." (PMID 26807257, 2016). "This CAR’s in vivo anti-tumor activity was similar whether signaling occurred via chimeric CD28 or CD137, prolonging survival in both AML and ALL models." (PMID 27548616, 2016). "Moreover, the Blina-RNA T cells showed superior in vitro anti-tumor activities compared with the RNA CAR T cells for both the CD3/CD28 bead and REP expansion methods." (PMID 27258611, 2016). "Indeed, by inhibiting CTLA-4 in 19z1-CD80+ T cells in which the CD28 signal comes from endogenous CD28 receptors activated by CD80 ligation, we almost reached the anti-tumor capacity of 19-28z+ T cells, in which CD28 costimulation is provided trough the CAR." (PMID 26110267, 2015). "BM cells from wild-type C57BL6 mice and the immune-deficient mouse strains B-cell−/−, CD28−/−, perforin−/−, and Rag2−/− but not CD11b−/− dramatically increased the expression of tumor cell surface PD-L1." (PMID 25889536, 2015). "However, TILs derived from the matched patients with cancer significantly down-regulated CD28 expression, further confirming the existence of elevated senescent T-cell populations in the tumor microenvironments." (PMID 25231413, 2014). "4-1BB signaling can co-stimulate T cells in a CD28-independent manner, protect tumor-infiltrating lymphocytes (TILs) from activation-induced cell death (AICD) via upregulation of antiapoptotic pathways, and enhance cytotoxic T lymphocyte (CTL) survival and cytolytic activity." (PMID 24855562, 2014). "However, addition of an exogenous agonistic anti-4-1BB IgG4 (BMS 663513) to the REP significantly enhanced the frequency and total yield of CD8+ T cells as well as their maintenance of CD28 and increased their anti-tumor CTL activity." (PMID 23560068, 2013). "Compared to beads, cell-based aAPCs bearing the costimulatory ligand CD137L can more efficiently induce the proliferation of antigen-experienced CD8+ CD28- T cells from peripheral blood and improve their in vivo persistence and antitumor activity upon adoptive transfer to tumor-bearing mice." (PMID 21827675, 2011). "Thus, incorporation of co-stimulation via NKG2D in addition to CD28 is essential to activate tumor or tissue-infiltrating effector CD8+ T cells." (PMID 20844584, 2010). "In this regard, TSA treatment can enhance the expression of NKG2D ligands on tumor cells, which may activate NK cell mediated immune responses and synergize with CD28 in inducing proliferation and IFN-γ production by CD8+ T cells." (PMID 18070359, 2007). "In melanoma metastases, CD28 down-regulation is more pronounced in areas of tumor regression." (PMID 15613231, 2004). "In addition, in patients with B-cell acute lymphoblastic leukemia (B-ALL) with a high rate of tumor load, CD28-based CAR-T induced a higher incidence of CRS and neurotoxicity, shorter long-term survival, and ineffective resistance to disease recurrence (NCT01044069)." (PMID 40181986, 2025).
tumor (continued). "CARs were studied that target various tumor antigens such as the B cell maturation antigen (BCMA), CD19, disialoganglioside GD2 (GD2), glypican-3 (GPC3) and epidermal growth factor receptor variant III (EGFRvIII), and contain different costimulatory domains including CD28 and 4-1BB 24–28." (PMID 38744947, 2025). "In addition, for the parallel mode of CD28 and 4-1BB, it was demonstrated that dual-targeted CAR-T carrying CD28 and 4-1BB sharing one CD3ζ had higher tumor-killing activity, dividing and proliferating ability and durability than the parallel mode of dual co-stimulatory molecules sharing two CD3ζ." (PMID 40181986, 2025). "Furthermore, the use of daratumumab can lead to the depletion of effector memory T cells and tumor-associated macrophages-type 1 as well as the downregulation of co-stimulatory CD28 expression on T cells, which altogether leads to further immunosuppression and worse control of tumor cells." (PMID 39857790, 2025). "Furthermore, we demonstrated that the significant association between the high expression of CD40 and the T-cell costimulatory molecules CD28 or GITR was most pronounced within the context of an "immunologically hot" tumor microenvironment, defined here by high CD4/CD8 RNA expression." (PMID 41182434, 2025). "Such broadly expressed tumor antigens may be more amenable to targeting with a CD28 TCE, with the natural avidity of the 2+1 format increasing the pool of antigens with therapeutic potential beyond the limited number of tumor-associated targets interrogated using CD3 TCEs." (PMID 39301613, 2025). "This may be attributed to the inadequate activation of T cells in the tumor microenvironment, such as insufficient CD28 costimulation signal, or the presence of immunosuppressive T cells in the immunosuppressive microenvironment, characterized by elevated levels of LAG3, PD-1, and TIM3." (PMID 39575257, 2024). "Many downregulated genes in tumour‐infiltrating peripheral CD8+ T cells are associated with classical IFN responses (IFI6, IFI27, MX1, STAT1, EPSTI1 PARP9, ISG15), cell proliferation (STMN1, CENPF, HELLS, NUSAP1, and DNPH1), and T cell costimulation (CD28, TMIGD2, TNFRSF4, CD27, and TNFRSF18)." (PMID 39350478, 2024). "In our model system, we simulated activated T cells with CD3/CD28 activation and cell to cell communication was limited to paracrine factors, therefore, future studies will need to investigate similar interactions in the context of tumor antigen specific T cells and cell-to-cell contact." (PMID 39414902, 2024). "Therefore, we hypothesize that pTCD8+CD28- level may reflect tumour immunity of the patients, thus aiding in the identification of individuals who are more likely to benefit from HER2-targeted therapy." (PMID 38519706, 2024). "Likewise, a recent study demonstrated that targeting sMIC alongside non-blocking antibodies could provide dual co-stimulation to antigen-specific CD8+ T cells through NKG2D and CD28, thereby improving the anti-tumor immunity." (PMID 39218939, 2024). "Therefore, CTLA-4 and CD28 soluble isoforms play vital roles in anti-tumor immune responses." (PMID 39218939, 2024). "Therefore, the addition of CD28 could potentially enhance the anti-tumor function, proliferation, and persistence of anti-BCMA-CAR3 T cells." (PMID 38683232, 2024). "In contrast, a slower velocity of T cell activation and cytotoxicity might prove beneficial for long-term effector function, as CD28 CARs showed increased exhaustion, reduced tumor elimination, and limited persistence in clinical settings compared to 4-1BB CARs." (PMID 38203786, 2024). "Therefore, a few of naïve-T cells might be activated in a tumor antigen-specific manner and induce immune killing after receiving both these tumor cells pMHC antigen signals and supplementary CD28 co-stimulatory activation signals." (PMID 39158647, 2024).
tumor (continued). "Treatment with anti-CLDN18.2-anti-CD28 also produced more interferon-γ (IFN-γ) and tumour necrosis factor-α (TNF-α) in splenocytes and reduced the levels of immunosuppressive cells, including tumour-associated macrophages and myeloid-derived suppressor cells, in tumour tissues." (PMID 36969060, 2023). "Thus, it is suggested that anti-CLDN18.2-anti-CD28 could play a tumour-killing role by improving antitumour immune response and attenuating the suppressive tumour microenvironment." (PMID 36969060, 2023). "A key aspect of tumor immune surveillance is that costimulatory or coinhibitory ligands, such as B7-1 or PD-L1, that interact with cognate costimulatory or coinhibitory receptors, such as CD28/CTLA-4 or PD-1, on T cells to elicit or suppress tumor-antigen-specific immune responses, respectively." (PMID 37662958, 2023). "Therefore, we can envision that CD28 may dictate the migration of long-lived memory effector CD8+ T cells to the tumor site." (PMID 37898752, 2023). "Similarly, it has been reported that CAR-T engineered to secrete checkpoint inhibitor antibodies or CAR-T expressing chimeric PD1/CD28 which switches inhibiting signal to costimulatory signal could improve anti-tumor efficacy in solid tumor settings." (PMID 37349298, 2023). "Although we did not assess markers for cell exhaustion, it might be speculated that γδT cells in patients have an altered functionality and less responsiveness to CD3/CD28 stimulation due to the tumor microenvironment and chronic stimulation with tumor antigens." (PMID 37187728, 2023). "Moreover, tumor-induced perturbations in TdLN-DCs could hamper cross-presentation of tumor antigen and CD28 co-stimulation of T cells." (PMID 38044445, 2023). "Next, we tested whether the expression of TMEM123 responded to T-cell receptor (TCR) activation via anti-CD3/CD28 T cell activation and to tumor microenvironmental stimuli known to affect fates and intrinsic pathways of T lymphocytes, relevant for trafficking, differentiation and function." (PMID 37426665, 2023). "Furthermore, prostaglandin E derived from tumor-activated Schwann cells blocked the proliferation of CD3/CD28-activated T cells and upregulated the expression of CD73 and PD-1 on both CD4+ and CD8+ T cells, suggesting T cell polarization to the exhausted phenotype." (PMID 36428970, 2022). "CARs are chimeric antigen-recognition receptors, consisting of an ectodomain, which binds a tumor specific cell surface receptor, and endodomains, consisting of CD3ζ as the signaling domain with co-stimulatory domains to provide robust activation (e.g. CD28, 4-1BB, or ICOS)." (PMID 35784326, 2022). "Due to their competition for binding to the ligands CD80 and CD86 and their antagonistic function in the control of the immune system, one could claim that the ratio of expression levels between CTLA-4 and CD28 in the tumor shifts towards CTLA-4, which would result in a higher CTLA-4/CD28 quotient." (PMID 35406584, 2022). "Moreover, the combination of PI3K inhibitors with CAR-T therapy is based on the rationale that CAR-T cells in vivo might become rapidly exhausted upon encounter with target-antigen on tumor cells and subsequent CD28 downstream signaling." (PMID 35681646, 2022). "Furthermore, CD28 expression has also been studied in ascites tumor-infiltrating lymphocytes." (PMID 35204342, 2022). "Therefore, in the context of different solid tumors, the anti-tumor functions of CD28 and 4-1BB-based CARs may vary." (PMID 35252208, 2022). "It is possible that the CD86/CD28 costimulatory signal primarily affected the survival and activation of memory CD4 T-cells, which were associated with OS and RFS and could kill tumor cells." (PMID 35463956, 2022). "However, the CD28 costimulatory domain may be needed to achieve high T cell activation rates during tumour infiltration." (PMID 36299480, 2022).